Y_RNA (Y RNA )
Gene: Miscellaneous RNA gene on chromosome 2 (216,351,403 to 216,351,504, forward strand). Ensembl gene ENSG00000207303.
Homologues: Orthologues: chimpanzee Y_RNA (96% identical), macaque Y_RNA (95% identical), guinea pig Y_RNA (91% identical). Paralogues in human: Y_RNA (91% identical), RNY3 (90% identical), Y_RNA (88% identical), RNY3P1 (87% identical), Y_RNA (87% identical), RNY3P16 (86% identical), Y_RNA (86% identical), RNY3P9 (85% identical), Y_RNA (85% identical), RNY3P14 (84% identical), RNY3P3 (84% identical), Y_RNA (84% identical), and 95 more.